EGFR (epidermal growth factor receptor)
Diseases named in the same sentence as EGFR in open-access papers (continued):
Sharing a sentence is not in itself a finding about the gene and the disease.
cancer (continued). "Although some crucial pathways (e.g., MAPK, Apoptosis, ERBB, JAK-STAT) were not top-ranked, core genes within these pathways (AKT1, EGFR, CASP3, TNF, SRC) showed high connectivity in the PPI network, reinforcing their relevance to the anti-cancer mechanisms of Siegesbeckiae Herba constituents." (PMID 41006588, 2025). "In the pan-cancer analysis, a decreased probability of overall survival (OS) and disease-specific survival (DSS) was found in amplified tumors in comparison with non-amplified ones, with EGFR, CDK4, MDM2, KRAS, and CCNE1-amplified tumors being those associated with a worse prognosis." (PMID 36980521, 2023). "This approach has been demonstrated in using an anti-EGFR antibody as a targeting ligand with CPP acting as an efficient facilitator of cellular uptake, resulting in specific delivery of siRNA to EGFR-positive cancer cells without impacting the viability or function of non-cancerous cells." (PMID 37848888, 2023). "Considering the role of glycosylation in cancer, it will be important to investigate the potential role of glycosylated EMP3 in the mitochondria and how it could influence GBM independent of EMP3’s effects on EGFR." (PMID 37936247, 2023). "Although the first generation TKI of ERBB1/EGFR have not shown meaningful clinical activity in cancer patients with wildtype ERBB1/EGFR or mutant ERBB1/EGFR with T790M, new-generation TKI such as Afatinib are active even against wildtype or T790M mutant ERBB1/EGFR." (PMID 36311273, 2022). "Therefore, YTHDF2 could display a negative effect in regulating the stability of EGFR and then affect the MAPK/ERK pathway, which inhibits the growth of cancer." (PMID 35382893, 2022). "In addition, enforced expression of TMEM52B isoforms in HCT-116 cells, which display little to no TMEM52B expression, reduced phosphorylation of EGFR, AKT, JNK, ERK1/2, and c-Jun along with reduced cancer cell invasion and survival, confirming the effects of the TMEM52B isoforms." (PMID 33641663, 2021). "Moreover, we also found that osimertinib alone did not affect pERK activity and increased pAKT expression in EGFR/MET-driven tumors, which could provide pro-survival signals to the cancer cells even in the absence of pEGFR." (PMID 34298655, 2021). "However, inhibitors of MAPK (Mitogen activated protein kinase), EGFR(Epidermal growth factor receptor), TGFβRI (Transforming growth factor receptor 1), and the CXCR4 (C-X-C chemokine receptor) did not inhibit conditioned medium-induced cancer cell scattering." (PMID 32731484, 2020). "As shown by the body of research presented so far, EGFR acts as a major cargo of EVs and participates, with co-expressed proteins and small RNA molecules, in EV uptake and reprogramming of bystander cells in the TME, contributing to most if not all of the hallmarks of cancer." (PMID 33228060, 2020). "Other new therapies instead reverse the immune tolerance towards cancer through the blockade of negative immune regulators such as PD-1/PD-1L and CTLA4 have enjoyed vast success in clinical trials of NSCLC and bypass the need of targeting EGFR specifically, providing an attractive therapeutic." (PMID 30959819, 2019). "Moreover, while considering its reported activity in EGF shedding, we specifically analyzed EGFR activation in cells overexpressing RHBDL2, but could not confirm this mechanism in our cancer cell models." (PMID 31783481, 2019). "Non-canonical Gli activation independent of Shh activation has also been noted in many cancer cells types, owing to stimulation by other oncogenic signaling pathways such as transforming growth factor β (TGF-β), epidermal growth factor receptor (EGFR), RAS, and AKT/PI3K." (PMID 29416661, 2018).
cancer (continued). "Although their frequencies were very low in our database analyses, the exact frequencies remain unknown because the COSMIC database includes cancer types other than NSCLC and most of the analyzed samples (both TCGA and COSMIC) had never been treated with EGFR-TKIs." (PMID 28424065, 2017). "Therefore, these HaCaT in vitro models exhibit the predicted signaling alterations expected by EGFR, RAS, and PI3K pathway activation without the complexity introduced by the broader genetic heterogeneity evident within the landscape of cancer cell lines or human tumors." (PMID 27650546, 2016). "The majority of known driver gene amplifications (e.g., EGFR, ERBB2, MET, and MYC) and homozygous deletions (e.g., CDKN2A, PTEN, and RB1) were captured, with 320 RACSs (38%) containing at least one known putative cancer driver gene, in addition to 531 RACSs (62%) without known driver genes." (PMID 27397505, 2016). "Soluble ectodomains of LRIG1 are reportedly sufficient to inhibit the growth of cancer cells by attenuating EGFR activity, and more recently, a study showed that the LRIG1 ectodomain can be naturally shed and can function as a non-cell-autonomous regulator of EGFR signaling." (PMID 24709893, 2014). "Basal-like cancers are characteristically negative for ER, PR and HER2 expression (i.e. triple negative) but may express basal cytokeratins (CK5-6 and CK14) and the epidermal growth factor receptor (EGFR)." (PMID 19773756, 2009). "In addition to the metabolic feature of UCK2 which has been employed for cancer treatment, our recent study has demonstrated that UCK2 can non-metabolically activating EGFR-AKT signaling to promote HCC progression, which may provide novel UCK2-based therapeutic strategies for cancer treatment." (PMID 35669416, 2022). "Moreover, the activation of EGFR and Ras signaling pathways was previously well known to promote cell proliferation and survival of certain tumors, so we further clarified that neither EGF nor cytokines induced senescence in cancer cell lines under our experimental conditions." (PMID 32323422, 2020). "In addition, it was observed that cetuximab could clearly downregulate HIF-1α levels in cancer cells that were sensitive to EGFR inhibition and it was shown that HIF-1α was required, although it might not be sufficient, to mediate the response of cancer cells to cetuximab." (PMID 26032726, 2015).
adenocarcinoma (1,717 papers, 1992 to 2026). A common cancer characterized by the presence of malignant glandular cells. "Subsequent biopsies confirmed the lung as the primary source of the adenocarcinoma (EGFR L858R mutation)." (PMID 41743956, 2026). "All of the patients enrolled were adenocarcinoma, for we go on EGFR mutation testing only in patients with adenocarcinoma after surgery." (PMID 40168285, 2025). "Further analysis of EGFR mutations at exon 19/21 sites showed higher mutation rates in moderately differentiated adenocarcinomas, particularly in lepidic and acinar subtypes, and low mutation rates in mucinous subtypes." (PMID 41378298, 2025). "Among the 18 patients with adenocarcinoma, the EGFR status was available for 10 (55.6%), with 2 patients (20%) presenting EGFR mutations." (PMID 39813498, 2025). "While our study highlights a prevalence of EGFR mutations in adenocarcinoma, variations in mutation rates based on gender, smoking status, and clinical factors suggest a need for further research, particularly with larger sample sizes." (PMID 40104451, 2025). "In recent years, it was reported that EGFR mutations were associated with longer survival in advanced adenocarcinoma." (PMID 40507634, 2025). "Adenocarcinoma is often associated with genetic mutations such as EGFR (epidermal growth factor receptor), ALK (anaplastic lymphoma kinase), and KRAS (Kirsten rat sarcoma viral oncogene homolog), making it a target for precision therapies." (PMID 40728967, 2025). "Adenocarcinomas frequently harbor mutations in EGFR, KRAS, B-Raf proto-oncogene (BRAF), and rearrangements involving ALK, c-ros oncogene 1 (ROS1), and rearranged during transfection (RET), which serve as critical predictive biomarkers and therapeutic targets." (PMID 41303058, 2025). "The predominance of EGFR mutations in adenocarcinoma highlights its potential as a therapeutic target for EGFR inhibitors." (PMID 40502411, 2025). "The RLL nodule showed poorly differentiated adenocarcinoma with a mostly solid pattern stage IA3 (pT1cN0M0) with an EGFR mutation." (PMID 40642683, 2025). "Prior to insurance coverage of multiplex tests in Japan, a systematic review of 33 Japanese studies reported that 45% of samples from patients with NSCLC of adenocarcinoma histology (2069/4619) were positive for EGFR mutation." (PMID 40941653, 2025). "Seventeen patients met inclusion criteria, all with adenocarcinoma histology and either EGFR exon 19 deletions or L858R mutations." (PMID 41175446, 2025). "This OS advantage was also observed in EGFR-mutated adenocarcinomas (36.7 vs. 27.2 months; HR 0.76, 95% CI: 0.66–0.87, p < 0.001)." (PMID 40940992, 2025). "Previous research by us and others has shown that most T-SCLCs retain their original EGFR mutation when transforming from EGFR-mutated adenocarcinomas during resistance to EGFR-TKIs." (PMID 40437627, 2025). "At our institution, the EGFR mutation detection rate for adenocarcinomas was 32%, which was lower than previously reported data." (PMID 39947926, 2025). "Adenocarcinoma was prevalent in 706 (66%) patients, with 218 (20%) exhibiting EGFR mutations and 304 (28%) with KRAS mutations." (PMID 41245885, 2025). "The overall cohort included 78.9% patients with NSCLC adenocarcinoma histology, 31.5% with PD-L1 score of 1+, 7% with +EGFR mutations, and 18.3% with +KRAS mutations." (PMID 40636413, 2025). "Survival analysis demonstrated that younger age, female sex, adenocarcinoma histology, p-stage II, low CD score, positive EGFR/ALK mutation, and ICI were associated with better OS in those who treated with adjuvant chemotherapy by univariate analysis." (PMID 40676423, 2025).
adenocarcinoma (continued). "A study of 102 cases of LCLC revealed that adenocarcinoma-associated mutations (EGFR, KRAS, BRAF, and ALK) occurred exclusively in the null immunophenotype or adenocarcinoma-differentiated LCLC." (PMID 40898486, 2025). "The EGFR mutation rate of 7.8% in adenocarcinomas observed in our study was lower than what is typically reported in the international literature, where EGFR mutations range from 10 to 15% in Western populations and up to 40% in Asian cohorts." (PMID 40867330, 2025). "Exon 19 deletions and missense p.L858R mutations of the EGFR gene have quite similar frequencies (46%) and were more observed in never smokers (p < 0.001) and female (p < 0.001) patients with the adenocarcinoma histotype." (PMID 40075579, 2025). "Adenocarcinomas frequently harbor driver mutations such as EGFR, KRAS, and ALK rearrangements, which modulate immune landscapes." (PMID 40342732, 2025). "This aligns with evidence suggesting that specific markers predict certain histology: CEA and CA 15-3 for adenocarcinoma, where EGFR mutations are more prevalent, and CYFRA 21-1 and SCC for squamous cell carcinoma." (PMID 40977812, 2025). "Given that EGFR mutation testing has therapeutic implications even at an early stage, routine testing has become essential in adenocarcinoma at an early stage." (PMID 40791752, 2025). "In accordance with previous studies, women, non‐smokers, and adenocarcinoma made up a higher proportion of all the patients with uncommon EGFR mutation." (PMID 39739938, 2025). "For instance, we were unable to look at the testing rates and associated survival for Asian patients who have a markedly higher rate of EGFR mutations than White patients, approximately 50% vs. 20%, respectively, in adenocarcinoma cases." (PMID 40429725, 2025). "SMARCA4-mutated patients tend to present with adenocarcinoma, a smoking history, and a low frequency of epidermal growth factor receptor (EGFR)/SMARCA4 co-mutations." (PMID 41007704, 2025). "For adenocarcinoma, many patients harboring EGFR mutations appropriately received molecularly targeted therapy as first-line treatment, which can limit the incremental benefit of ICIs." (PMID 41008908, 2025). "Materials and Methods: Blood samples from 35 patients with EGFR-mutated (EGFRmut) adenocarcinoma who achieved disease control with EGFR tyrosine kinase inhibitor (EGFR TKI) therapy were collected for sPD-L1 analysis." (PMID 39852160, 2025). "Results showed that the EGFR mutation rate was obviously lower in adenocarcinoma patients with IPF compared to those with normal lungs (16.3% vs. 50.9%, p = 0.000)." (PMID 40507634, 2025). "In this study, the EGFR mutation rate was significantly lower in patients with IPF combined with adenocarcinoma." (PMID 40507634, 2025). "Pancreatic metastases were documented in 75 NSCLC cases, with only 10 having EGFR-mutated adenocarcinoma." (PMID 40656425, 2025). "The most common driver gene mutation in NSCLC is EGFR, which occurs in 45 % of Asian patients and 20 % of Caucasian patients with adenocarcinoma histology." (PMID 40144458, 2025). "With the use of TKIs, patients with EGFR-mutated adenocarcinoma experience the progression of their disease after months or years of treatment." (PMID 40076686, 2025). "Of the 61 patients included in the study, the mean age of prevalence of EGFR mutation in adenocarcinoma was 58.13 years, with a prevalence rate of 31.1%." (PMID 40104451, 2025). "This is likely due to a higher rate of smoking in North Africa making EGFR mutations less likely despite similar rates of adenocarcinoma." (PMID 40112503, 2025).
adenocarcinoma (continued). "Another study constructed an integrated model using CT radiomics, CT radiological features and clinical features to predict EGFR mutations in adenocarcinoma patients, achieving AUCs of 0.849 and 0.835 in the training and validation groups, respectively." (PMID 40242240, 2025). "Adenocarcinoma was the most common sub-type in 85.4 % (n = 105) patients and 60 % of cases had EGFR testing done and a mutation was detected in 35 % (n = 26/74) patients tested." (PMID 40112503, 2025). "For example, KRAS and EGFR mutations frequently occur in adenocarcinoma, while SCC has a much lower prevalence of these mutations." (PMID 38994972, 2024). "The median OS reported in clinical trials in the first-line setting with gefitinib (for EGFR-mutated adenocarcinoma) was 18.6 months, and with alectinib (for ALK-rearranged adenocarcinoma), it was not reached after close to 50 months of follow-up." (PMID 39123495, 2024). "Epidermal growth factor receptor (EGFR) mutation testing is recommended with adenocarcinoma histology." (PMID 39199613, 2024). "In our study of stage III NSCLC, the EGFR mutation status was mainly assessed in patients with adenocarcinomas prior to first‐line therapy and only six (15.8%) of those patients were positive." (PMID 38812106, 2024). "Binary logistic regression analysis revealed that age <50 years and adenocarcinoma type were significant predictors of EGFR mutations." (PMID 39429333, 2024). "Studies have shown varying frequencies of EGFR mutations in adenocarcinoma patients, with approximately 15% in the US and up to 51.4% in Asian populations." (PMID 39429333, 2024). "In a European study with only 14 patients, EGFR mutations were detected in 29% of ASCs, which even exceeds the mutation rates of adenocarcinomas." (PMID 39407771, 2024). "Approximately 60% of NSCLC patients with adenocarcinoma harbor oncogenic driver mutations, with the epidermal growth factor receptor (EGFR) mutation being the most commonly found and targetable driver mutation in NSCLC." (PMID 38454923, 2024). "Twenty-five patients had adenocarcinoma (89.3%), six had EGFR mutations (21.4%) and two had ALK mutations (7.1%)." (PMID 39445449, 2024). "EGFR is highly expressed in high-differentiated alveolar type II cells, which can be the origin for adenocarcinoma cells carrying EGFR gene mutations." (PMID 37436674, 2024). "A549 cells are adenocarcinoma cells that harbor KRAS G12S mutation but wildtype EGFR, whereas H1975 harbors EGFR mutations L858R and T790M." (PMID 39201772, 2024). "In patients with adenocarcinoma, the EGFR and KRAS mutation rates were 52.79% and 10.12%, respectively." (PMID 39364008, 2024). "EGFR mutations are predominantly found in adenocarcinoma, but they can also be detected in 54.8% of ASC patients." (PMID 39026979, 2024). "Our brain metastasis model has the potential to more accurately predict EGFR mutation/HER2 + status in patients with adenocarcinoma compared with models predominantly focused on primary lesions." (PMID 38773634, 2024). "Among adenocarcinomas EGFR mutations are frequently detected in cases with lepidic and papillary growth patterns." (PMID 38953007, 2024). "Epidermal growth factor receptor (EGFR) gene mutation tests were performed in 34.9% (52/149) of patients prior to first‐line treatment, including 38 patients with adenocarcinoma, nine with SCC, and five with other histological types." (PMID 38812106, 2024). "In our study, NSCLC (94.7%), especially adenocarcinoma, was common, and many of these cases expressed EGFR mutations, similar to previous reports." (PMID 39355485, 2024). "A total of 153 patients (87.9%) had adenocarcinoma; 38 (21.8%) had epidermal growth factor receptor (EGFR) mutations, and 52 (23%) developed liver metastases." (PMID 38686383, 2024). "Typically, patients with SMARCA4-deficient NSCLC clinically present with adenocarcinoma, larger invasive tumor size, a smoking history, and fewer epidermal growth factor receptor (EGFR) mutations (p < 0.05)." (PMID 39063938, 2024).